OTUB1 (OTU deubiquitinase, ubiquitin aldehyde binding 1)
Description:
Hydrolase that can specifically remove 'Lys-48'-linked conjugated ubiquitin from proteins and plays an important regulatory role at the level of protein turnover by preventing degradation. Regulator of T-cell anergy, a phenomenon that occurs when T-cells are rendered unresponsive to antigen rechallenge and no longer respond to their cognate antigen. Acts via its interaction with RNF128/GRAIL, a crucial inductor of CD4 T-cell anergy. Isoform 1 destabilizes RNF128, leading to prevent anergy. In contrast, isoform 2 stabilizes RNF128 and promotes anergy. Surprisingly, it regulates RNF128-mediated ubiquitination, but does not deubiquitinate polyubiquitinated RNF128. Deubiquitinates estrogen receptor alpha (ESR1). Mediates deubiquitination of 'Lys-48'-linked polyubiquitin chains, but not 'Lys-63'-linked polyubiquitin chains. Not able to cleave di-ubiquitin. Also capable of removing NEDD8 from NEDD8 conjugates, but with a much lower preference compared to 'Lys-48'-linked ubiquitin. Plays a key non-catalytic role in DNA repair regulation by inhibiting activity of RNF168, an E3 ubiquitin-protein ligase that promotes accumulation of 'Lys-63'-linked histone H2A and H2AX at DNA damage sites. Inhibits RNF168 independently of ubiquitin thioesterase activity by binding and inhibiting UBE2N/UBC13, the E2 partner of RNF168, thereby limiting spreading of 'Lys-63'-linked histone H2A and H2AX marks. Inhibition occurs by binding to free ubiquitin: free ubiquitin acts as an allosteric regulator that increases affinity for UBE2N/UBC13 and disrupts interaction with UBE2V1. The OTUB1-UBE2N/UBC13-free ubiquitin complex adopts a configuration that mimics a cleaved 'Lys48'-linked di-ubiquitin chain. Acts as a regulator of mTORC1 and mTORC2 complexes. When phosphorylated at Tyr-26, acts as an activator of the mTORC1 complex by mediating deubiquitination of RPTOR via a non-catalytic process: acts by binding and inhibiting the activity of the ubiquitin-conjugating enzyme E2 (UBE2D1/UBCH5A, UBE2W/UBC16 and UBE2N/UBC13), thereby preventing ubiquitination of RPTOR. Can also act as an inhibitor of the mTORC1 and mTORC2 complexes in response to amino acids by mediating non-catalytic deubiquitination of DEPTOR.
Synonyms: OTB1; OTU1; HSPC263; FLJ20113; FLJ40710
Tractability: PROTAC: ubiquitination databases record sites on it; its protein half-life has been measured.
Target class: Enzyme; Hydrolase
Gene: Protein-coding gene on chromosome 11 (63,985,853 to 64,001,811, forward strand). Ensembl gene ENSG00000167770.
Subcellular location: Cytoplasm
Subcellular location (Human Protein Atlas): Cytosol; Cytoplasmic bodies
Pathways (Reactome):
Metabolism of proteins: Ovarian tumor domain proteases; Ub-specific processing proteases
Gene Ontology:
Molecular function: cysteine-type deubiquitinase activity; deNEDDylase activity; protein binding; ubiquitin binding; ubiquitin protein ligase binding; ubiquitin-protein transferase inhibitor activity; hydrolase activity
Biological process: DNA damage response; negative regulation of double-strand break repair; positive regulation of TORC1 signaling; protein deubiquitination; protein K48-linked deubiquitination
Cellular component: extracellular exosome; cytoplasm; cytosol; nucleoplasm
Genetic constraint (gnomAD): Loss-of-function variants: 10 observed, 30.84 expected, observed/expected ratio (o/e) 0.32, 90% interval 0.2 to 0.55. The upper end of that interval is the gene's LOEUF score, 0.55, which puts it in group 2 of 6, group 1 being the genes least tolerant of losing a copy. Missense variants: 254 observed, 339.24 expected, observed/expected ratio (o/e) 0.75, 90% interval 0.68 to 0.83. Synonymous variants: 155 observed, 142.07 expected, observed/expected ratio (o/e) 1.09, 90% interval 0.96 to 1.25.
Homologues: Orthologues: dog OTUB1 (100% identical), pig OTUB1 (100% identical), guinea pig OTUB1 (99% identical), mouse Otub1 (99% identical), rat Otub1 (99% identical), rat Otub1l1 (95% identical), chimpanzee OTUB1 (87% identical), zebrafish otub1b (79% identical), zebrafish otub1a (78% identical), tropical clawed frog otub1 (75% identical), Drosophila melanogaster CG4968 (52% identical), Caenorhabditis elegans otub-1 (37% identical). Paralogues in human: OTUB2 (39% identical).
Diseases named in the same sentence as OTUB1 in open-access papers:
OTUB1 is named in the same sentence as 99 diseases in open-access papers, as found by Europe PMC text mining. Sharing a sentence is not in itself a finding about the gene and the disease. The quoted sentences say what the papers report.
breast carcinoma (26 papers, 2016 to 2025). "Our study investigated the effects and underlying mechanisms of OTUB1 on the breast cancer cell cycle and proliferation in IFNγ stimulation." (PMID 38664499, 2024). "Consistently, loss of OTUB1 leads to PD-L1 reduction in breast cancer cells, enhancing their sensitivity to the cytotoxicity of immune cells." (PMID 34575114, 2021). "Despite not being an independent prognostic marker in Kaplan–Meier survival analysis, OTUB1 is significantly associated with poorer prognosis in multivariate regression analysis, particularly in breast cancer patients who have received chemotherapy." (PMID 26148240, 2016). "This argues that OTUB1 is likely to be linked to chemotherapy sensitivity in breast cancer." (PMID 26148240, 2016). "These opposing effects highlight the cell type-specific regulatory mechanisms of OTUB1 in breast cancer." (PMID 40469292, 2025). "The dual roles of OTU family members in specific cancers present intriguing mechanistic complexities, exemplified by OTUB1 in breast cancer, OTUD7B in lung cancer, and TNFAIP3 in CRC." (PMID 40469292, 2025). "In breast cancer, for instance, OTUB1, YOD1, OTUD5, OTULIN, TNFAIP3, and ZRANB1 drove chemoresistance, whereas OTUD1 and OTUD3 were sensitized to chemotherapy." (PMID 40469292, 2025). "In the A549 lung cancer and 4T1 breast cancer mouse models, OTUB1 knockdown significantly enhanced the anti-tumor immune response of mice." (PMID 40469292, 2025). "OTUB1 is overexpressed in a wide variety of human tumors, such as colon cancer, gastric cancer, bladder and breast cancer." (PMID 38653740, 2024). "In this study, we identified OTUB1 as a new regulator of breast cancer by stabilizing the tumour suppressor CCN6." (PMID 37608493, 2023). "In human breast cancer samples, OTUB1 expression levels were positively correlated with that of CCN6." (PMID 37608493, 2023). "Given that CCN6 acts as a suppressor of breast cancer and its protein stability is enhanced by OTUB1, we investigated the impact of OTUB1 on breast cancer cells in vitro." (PMID 37608493, 2023). "To study the impact of OTUB1 on breast cancer in vivo, we established the mouse allograft model by subcutaneously injecting control, OTUB1−/− and OTUB1−/− + CCN6 (OTUB1−/− cells transfected with CCN6‐overexpressing plasmids) 4T1 cells in nude mice." (PMID 37608493, 2023). "In aggregate, these results show that OTUB1 inhibits the aggressive phenotypes, including migration, proliferation and viability, of breast cancer cells by upregulating CCN6 protein abundance." (PMID 37608493, 2023). "Consistently, silencing OTUB1 decreases breast cancer growth which can be counteracted by c-Myc overexpression in breast cancer cells MCF7 and MDA-MB-231." (PMID 38264570, 2023). "CircBGN directly binds to OTUB1 and SLC7A11, enhancing OTUB1-mediated SLC7A11 deubiquitination to inhibit ferroptosis in breast cancer." (PMID 37686142, 2023). "Our finding that the protein levels of OTUB1 and CCN6 are reduced in aggressive breast cancer suggests that the protein levels of OTUB1 in cancer tissues are more valuable for the prognosis of breast cancer." (PMID 37608493, 2023). "The authors showed OTUB1 knockout increases the proliferation and migration of 4T1 mouse breast cancer cells, which can be counteracted by CCN6 expression." (PMID 38264570, 2023). "Taken together, these findings demonstrate that OTUB1 suppresses the growth of breast cancer in vivo by increasing the protein levels of CCN6." (PMID 37608493, 2023). "In conclusion, the NF-κB/p65/CSN5/PD-L1, GATA3-AS1/miR-676-3p/CSN5/PD-L1, and OTUB1/PD-L1 axis promotes the immunosuppression of breast cancer." (PMID 34575114, 2021).
breast carcinoma (continued). "More interestingly, OTUB1 was shown to promote deubiquitination of FOXM1 in breast cancer and ovarian cancer to facilitate tumor progression." (PMID 32257108, 2020). "OTUB1 is overexpressed in prostate cancer, ovarian cancer, breast cancer, ESCC, HCC, gastric and CRC." (PMID 31737118, 2019). "The physiological relevance of the regulation of FOXM1 by OTUB1 is underscored by the strong and significant association between FOXM1 and OTUB1 in breast cancer patient samples." (PMID 26148240, 2016). "This is likely to be due to the complex role played by OTUB1 in breast cancer, as it regulates the expression and activity of a variety of substrate proteins with diverse and sometimes opposing functions in breast cancer initiation, progression and treatment." (PMID 26148240, 2016). "The discrepancy between breast cancer and other cancer types is likely because OTUB1 substrates, in particular ERα, have a particularly essential role in breast cancer initiation, progression and treatment." (PMID 26148240, 2016). "Importantly, OTUB1 expression was downregulated in human breast cancer and positively correlated with CCN6 levels." (PMID 37608493, 2023). "Supplementation of CCN6 abolished the effect of OTUB1 deletion on breast cancer." (PMID 37608493, 2023). "In addition, OTUB1 suppressed the aggressive phenotypes of breast cancer both in vitro and in vivo by elevating CCN6 levels." (PMID 37608493, 2023). "Besides, OTUB1 was also strongly reduced in breast cancer tissues as compared to adjacent normal breast tissues." (PMID 37608493, 2023). "However, considering the discrepancies between former reports and the present study, the clinical role of OTUB1 in breast cancer should be treated with more caution and further clinical studies are definitely required." (PMID 37608493, 2023). "To confirm this finding, we transfected human breast cancer cells with OTUB1 siRNA." (PMID 37608493, 2023). "This study identified OTUB1 as a novel regulator of CCN6 in breast cancer." (PMID 37608493, 2023). "Recently, OTUB1 has been found as a novel DUB of PD-L1 in breast cancer." (PMID 34575114, 2021). "Similarly, OTUB1 positively regulates PD‐L1 stabilization through deubiquitylation in human breast cancer." (PMID 34773364, 2021). "OTUB1 may also affect the stability of proteins, which contribute towards breast cancer progression and treatment." (PMID 26148240, 2016). "Notably, OTUB1 exhibits context-dependent functional duality in breast cancer progression." (PMID 40469292, 2025). "Accumulating evidence has shown that depletion of OTUB1 sensitizes multiple tumor cells to ferrotopsis, including glioma 141, colon cancer 142, breast cancer 143, and pancreatic cancer 144, thereby modulating OTUB1 might be a promising strategy for cancer therapy." (PMID 36147464, 2022). "Mechanistically, OTUB1 attenuated tumor immunity in NSCLC and breast cancer by cleaving the K48-Ub of PD-L1 to prevent degradation of PD-L1 via the ERAD pathway." (PMID 40469292, 2025). "Studies have shown that OTUB1 can deubiquitinate the MYC protein, making it a potential target for breast cancer treatment." (PMID 40387552, 2025). "To substantiate this finding in human breast cancer cells, we transfected MDA‐MB‐231 and BT549 cells with OTUB1 siRNA." (PMID 37608493, 2023). "The correlation of OTUB1 and CCN6 in human breast cancer was determined by immunohistochemistry and Western blot." (PMID 37608493, 2023). "Together, our results reveal a novel and critical role of OTUB1 in regulating CCN6 stability and breast cancer." (PMID 37608493, 2023). "In this study, we found that OTUB1 inhibited the aggressive phenotypes of breast cancer by stabilizing CCN6, a specific and potent suppressor in breast cancer." (PMID 37608493, 2023). "It is noteworthy that the significance of both OTUB1 and YAP has been underscored in lung, gastric, and breast cancers." (PMID 37986681, 2023).
breast carcinoma (continued). "Deletion of OTUB1, concomitant with reduced CCN6 abundance, increased the migration, proliferation and viability of breast cancer cells." (PMID 37608493, 2023). "In this study, we examined the potential role of OTUB1 in the regulation of FOXM1 expression in genotoxic drug-sensitive and -resistant breast cancer cells." (PMID 26148240, 2016). "The physiological relevance of the regulation of FOXM1 by OTUB1 is further underscored by the significant correlations between FOXM1 and OTUB1 expression in breast cancer patient samples." (PMID 26148240, 2016). "Indeed, it has been reported that OTUB1 could enhance breast cancer chemoresistance." (PMID 27167337, 2016). "Importantly, TCGA data analysis revealed that, similarly to lung adenocarcinomas, OTUB1 overexpression in colorectal cancer is mutually exclusive with KRAS mutations (co‐occurrence log odds ratio: −3; P‐value: 0.003), whereas RAS genes are rarely mutated in prostate and breast cancers." (PMID 26881969, 2016). "Collectively, these data suggest that OTUB1 limits the ubiquitination and degradation of FOXM1 in breast cancer and has a key role in genotoxic agent resistance." (PMID 26148240, 2016). "Furthermore, OTUB1 and OTUD6A deubiquitinated and stabilized CHK1 and TopBP1, which regulated DNA damage and repair and promoted radiation resistance in lung and breast cancer, respectively." (PMID 40469292, 2025). "For example, OTUB1 can inhibit breast cancer growth and invasiveness via nonclassical mechanisms, while OTUD6B can suppress liver cancer metastasis independently of its enzymatic activity." (PMID 39678489, 2024). "OTUB1 mRNA levels were not significantly correlated with the survival time of patients with breast cancer." (PMID 37608493, 2023). "Similar to findings obtained with 4T1 cells, knockdown of OTUB1 significantly reduced CCN6 protein levels in these human breast cancer cells, but did not influence mRNA levels of CCN6." (PMID 37608493, 2023). "Mainly USP4, USP7, USP22, UCHL1, UCHL5, and OTUB1 could be used as biomarkers for each type of cancer such as EOC, breast cancer, melanoma, cervical cancer, and colorectal cancer." (PMID 37107644, 2023). "In addition, we identified OTUB1 as a bona fide DUB for CCN6, and OTUB1 played a key role in breast cancer by regulating CCN6 protein levels." (PMID 37608493, 2023). "OTUB1 can also inhibit the ubiquitination of FOXM1, stabilize FOXM1 protein levels, downregulate FOXM1 protein levels in breast cancer, and increase the sensitivity of breast cancer cells to chemotherapeutic agents." (PMID 35494004, 2022). "OTUB1 was reported to inhibit the ubiquitination of FOXM1 in ovarian cancer and breast cancer." (PMID 32257108, 2020). "To explore the potential regulation of FOXM1 by OTUB1 in response to genotoxic agents, we investigated the expression of OTUB1 and FOXM1 in the epirubicin-sensitive MCF-7 and epirubicin-resistant MCF-7EpiR breast carcinoma cell lines following epirubicin treatment." (PMID 26148240, 2016). "Given that OTUB1 is a deubiquitinating enzyme that removes polyubiquitin chains and promotes stability of target proteins, these data suggest that OTUB1 binds to FOXM1 and modulates its ubiquitination and degradation in response to genotoxic treatment in breast cancer." (PMID 26148240, 2016). "Moreover, OTUB1 and OTUD1 act as tumor suppressors in breast cancer." (PMID 39678489, 2024). "Besides, ablation of OTUB1 significantly increased the proliferation and viability of 4T1 cells, while overexpression of CCN6 in OTUB1−/− cells reversed the effect, suggesting that OTUB1 inhibits breast cancer proliferation and viability by elevating CCN6 levels." (PMID 37608493, 2023).